DKK1 (dickkopf Wnt signaling pathway inhibitor 1)
Diseases named in the same sentence as DKK1 in open-access papers (continued):
Sharing a sentence is not in itself a finding about the gene and the disease.
tumor (continued). "At later stages in human tumors, systemic therapy can cause the selection of tumor cells with high nuclear DKK-1 that by inducing genes such as ALDH1A1 and REPS2 may be responsible for chemoresistance." (PMID 25788273, 2015). "The heterogeneity of DKK-1 protein expression within the tumour may limit the diagnostic value of DKK-1 assessment from biopsies of the primary cancer and also explains the lack of correlation between tumour and serum DKK-1 levels." (PMID 25182503, 2014). "Similarly, Dkk1 was found to be absent from choriocarcinoma cells and re-expression of the gene induced growth arrest and apoptosis suggesting that the loss of Dkk1 is critical for tumor cell proliferation." (PMID 24133501, 2013). "Numerous studies have shown that DKK1 was implicated in the control of various pathological and physiological processes, including adult hippocampal neurogenesis, osteoclastogenesis, tumor cell proliferation, survival, migration and invasion." (PMID 24325363, 2013). "Again, DKK-1 caused fewer and smaller tumor foci vs. control." (PMID 21317455, 2010). "Moreover, a DKK1 neutralizing antibody demonstrated anti-tumor effects in immune-deficient mice." (PMID 40025612, 2025). "Previous studies demonstrated that the mechanisms of immune resistance to ICIs might involve mutations in the Wnt/β-catenin pathway, PI3K-AKT-mTOR pathway, CDH1 gene, elevated expression of Dickkopf 1 (DKK1), and heterogeneity in tumor mutation burden and tumor microenvironment." (PMID 36291942, 2022). "Therefore, it remains unclear whether tumor-associated DKK-1 expression is more substantial than systemic endogenous expression in bone tissue." (PMID 30116403, 2018). "Also, it remains unclear whether increases in DKK-1 during the course of a disease are associated with tumor progression." (PMID 24528599, 2014). "Next, we aimed to investigate if loss of DKK1 may influence tumor cell proliferation." (PMID 24325363, 2013). "Furthermore, the inactivation of Dkk1 seems to predispose to neoplasias in the proximal colon." (PMID 24204690, 2013). "Furthermore, in line with our current findings, which suggests that DKK1 may act as a feed-back tumor suppressor, these authors also reported loss of DKK1 protein expression in a subgroup of patients with advanced MM." (PMID 22363428, 2012). "Focally increased Dkk1 production by tumor cells in the bone may thus lead to focal bone loss." (PMID 17971207, 2007). "In vivo xenograft and metastatic models showed that GPx3 suppressed tumor growth and metastasis, and these effects were partially reversed by DKK1." (PMID 42125307, 2026). "DKK1 was predominantly expressed by epithelial tumor cells and tracked along a malignant progression continuum." (PMID 41751444, 2026). "Although it functions as a tumor suppressor in some specific biological background and disease stages, growing evidence links DKK1 to tumor progression, immune evasion, and therapy resistance in a variety of multiple malignancies." (PMID 42122171, 2026). "The molecular mechanisms by which DKK1 promotes tumor progression, metastasis, and immune evasion are driven by its interaction with cell-surface receptors, specifically LRP5/6 and CKAP4." (PMID 42123366, 2026). "By prioritizing the literature from the last decade, this review characterizes DKK1 as a key mediator of tumor progression and immune reprogramming, while assessing its clinical potential as a biomarker and therapeutic target." (PMID 42123366, 2026). "In lung cancer, particularly those with c-Met activation, the pharmaceutical blockade of c-Met resulted in reduced tumor growth via suppression of DKK1 expression." (PMID 39795613, 2025). "The therapeutic strategy of evaluating a combination of DKK1 and an immune checkpoint inhibitor is promising for tumor patients with high DKK1 expression." (PMID 40943055, 2025).
tumor (continued). "Direct effects of DKK1 on tumor cells have been described in head and neck cancer, pancreatic ductal adenocarcinoma, and esophageal squamous cell carcinoma." (PMID 39885132, 2025). "Despite this controversy, recent evidence points to an immunomodulatory role for DKK1 in the tumor microenvironment." (PMID 40394415, 2025). "Our study demonstrates that resistance of mesenchymal-like TNBC cells is associated with down regulation of BIRC5 (survivin) and upregulation of CXCL8/IL-8 and M-CSF while that of epithelial tumor cells is associated with upregulation of CTSS, MCP-1 and DKK-1." (PMID 41279138, 2025). "High DKK1 expression in GC correlates with tumor progression, poor prognosis, and an immunosuppressive TME characterized by increased M2 macrophages and reduced antitumor CD4+ T and NK cells." (PMID 40686307, 2025). "Local production of DKK1 at the tumor site limits tumor immune infiltration, and DKK1 neutralization or its deletion in CAFs reverses these effects." (PMID 39885132, 2025). "Taking this fact into account, the DKK1 function seems to be dictated by the receptor setting of the tumor cells." (PMID 39795613, 2025). "At the same time, DKN-01 in combination with pembrolizumab showed a favorable safety profile, while the anti-tumor efficacy was superior mainly in anti-PD-1/PD-L1-naïve patients with high expression of DKK1." (PMID 39795613, 2025). "Our findings demonstrate the importance of monitoring various sources of DKK1 during tumor progression." (PMID 39885132, 2025). "FMRP interacts with both GSK3β and CTNNB1, MSI1 represses APC and enhances Wnt signaling in epithelial progenitors, while MEX3A stabilizes LGR5 and represses DKK1, thereby promoting stemness and tumor progression." (PMID 41516083, 2025). "In Lewis lung carcinoma and melanoma mouse models, antibody-mediated neutralization of DKK1 reduced tumor growth and myeloid-derived suppressor cell (MDSC) accumulation in a β-catenin-dependent manner." (PMID 40394415, 2025). "The study demonstrated that inhibiting DKK1 remodeled the tumor microenvironment (TME), facilitating immune cell infiltration and enhancing responsiveness to ICIs, especially in immunologically “cold” tumors." (PMID 41373587, 2025). "An immunosuppressive TME is linked to DKK1 overexpression in CRC, making it harder for the immune system to mount a successful anti-tumor response." (PMID 39788945, 2025). "We show that cancer-associated fibroblasts (CAFs) contribute to the production of DKK1 in the tumor microenvironment (TME), and bone cells contribute to systemic DKK1 elevation." (PMID 39885132, 2025). "The anti-tumor effects of DCC-2036 on CRC are mediated by its capacity to activate anti-tumor T-cell immunity via the FGR/AKT/SP1/DKK1 axis." (PMID 39788945, 2025). "In high-risk patients, APOD, OLR1, STC2, and DKK1 were found to be overexpressed, with APOD showing tumor-suppressive effects in certain cancers, while OLR1, STC2, and DKK1 are known to promote tumor growth and immune suppression." (PMID 39857718, 2025). "DKK1 altered fibroblast characteristics, enhancing inflammatory fibroblast traits while diminishing myofibroblast traits in tumor microenvironment." (PMID 40025612, 2025). "TdT+ CAFs, isolated from orthotopic tumors in αSMA-Dkk1WT-tdT mice, reduced the NK-mediated tumor killing, and DKK1 neutralization restored NK cell functionality." (PMID 39885132, 2025). "Targeting DKK1 or CKAP4 results in increased accumulation of cytotoxic T-cells in tumor lesions as well as improved ability of the macrophages to activate cytotoxic lymphocytes." (PMID 41149482, 2025). "Here, we found that DKK1 expression and secretion were significantly increased in gefitinib-resistant NSCLCs, highlighting the role of DKK1 in the specific tumor microenvironment." (PMID 40025612, 2025). "For example, cancer cell-derived DKK1 can inhibit the tumor infiltration of macrophages and neutrophils resulting in the immune suppressive TME." (PMID 40025612, 2025).
tumor (continued). "Both bone- and CAF-derived DKK1 suppress NK cell cytotoxicity, and their targeting reduces tumor progression." (PMID 39885132, 2025). "The clinical findings also assessed that in the combination treatment with DKN-1 and pembrolizumab, patients with an elevated DKK1 level in the tumor demonstrated relatively higher efficacy than those with a low level." (PMID 40943055, 2025). "DKK‐1 activates the Akt pathway to promote tumour progression, cell survival, and protease production for cancer cell migration." (PMID 40116596, 2025). "While Dkk1 transcripts were only detected in the 4T1 tumor cell line in vitro, Dkk1 was found in the tumor mass of PyMT and E0771 models." (PMID 39885132, 2025). "Atezolizumab is a PD-L1 targeting antibody; nevertheless, it is associated with reduced efficacy when FGR and DKK1 levels are high, according to TISIDB, a database that documents tumor-immune interactions." (PMID 39788945, 2025). "Since T cell depletion did not alter the anti-tumor effects of mDKN01, findings in Prf1−/− mice suggest that DKK1 supports tumor progression through suppression of NK cell function." (PMID 39885132, 2025). "Among the top 100 deregulated genes, Wnt-associated genes such as LGR5, DKK1, and NKD1, as well as the HB-related genes DUSP9, DLK1, PEG3, PEG10, IGF2BP1, and IGF2BP2 were consistently upregulated in tumor samples." (PMID 40968384, 2025). "In CRC, sh-RNAs targeting CKAP4 have the ability to suppress both DKK1 and Akt levels, and tumor and colony formation." (PMID 41149482, 2025). "Strikingly, we found a significant decrease in tumor growth in mice co-injected with Dkk1 null CAFs compared to those co-injected with Dkk1-sufficient CAFs." (PMID 39885132, 2025). "While Dickkopf-1 (DKK1) is classically recognized as a Wnt signaling antagonist, emerging evidence highlights its paradoxical role in promoting tumor progression, immune evasion, and angiogenesis." (PMID 41373587, 2025). "We used a co-culture system that included MC-38 CRC cells and CD8+ T lymphocytes to determine how DKK1 affects T cell dynamics in the tumor microenvironment (TME)." (PMID 39788945, 2025). "We confirmed that cancer cell-derived DKK1 facilitates interactions between cancer cells and fibroblasts, thereby promoting tumor growth." (PMID 40025612, 2025). "In a murine model, treatment with the anti-DKK1 mAb DKN-01 was found to stimulate innate immunity responses in the tumor microenvironment and had synergistic effects with PD-1 inhibitors." (PMID 39941712, 2025). "Consistently with the in vitro findings, Western blotting and qRT-PCR analysis revealed that TP-0903 administration significantly downregulated the protein level and mRNA expression of DKK1 in the tumor derived from inoculated Neuro-2a cells (P < 0.01)." (PMID 40804038, 2025). "Cancer cell-derived DKK1 mediates the interaction between cancer cells and fibroblasts, resulting in changes in fibroblast characteristics and subsequent tumor progression." (PMID 40025612, 2025). "Here, we propose Dickkopf-1 (DKK1) as a key secretory protein influencing the tumor microenvironment in gefitinib-resistant cancer." (PMID 40025612, 2025). "By using genetic approaches, we find that bone-derived DKK1 contributes to the systemic DKK1 elevation in tumor-bearing female mice, while CAFs contribute to DKK1 at primary tumor site." (PMID 39885132, 2025). "Functional characterization reveals that SLPI-expressing AT2-like cells upregulated Dickkopf-1(DKK1), enhancing tumor cell stemness and epithelial-mesenchymal transition (EMT)." (PMID 41216859, 2025). "Having established that DKK1 CRD1 binders suppressed tumor growth in vitro, we tested their efficacy in this xenograft model." (PMID 40394415, 2025). "DKK1 seems to have immunomodulatory effects in the tumor microenvironment, inducing immunosuppression and a low anti-tumor response by impeding a Natural Killer (NK) cell-mediated response and enhancing myeloid-derived suppressor cell activity." (PMID 39795613, 2025).
tumor (continued). "In both comparisons, the most pronounced genes in WNT signaling‐related pathways are DKK4 and DKK1, as in both comparisons, these two genes were highly upregulated in G3 tumor." (PMID 39245631, 2025). "Several reports have shown that NK cells play important roles in suppressing tumor growth during DKK1-mediated immunosuppression and cancer progression." (PMID 40394415, 2025). "Through the activation of Ak strain transforming (AKT), the secretory protein Dickkopf‐1 (DKK1) binds to cytoskeleton‐associated membrane protein 4 (CKAP4), which in turn stimulates tumor growth." (PMID 39757782, 2025). "Our findings indicate that DKK1 represents a barrier to anti-tumor immunity through suppression of NK cells." (PMID 39885132, 2025). "In fact, DKK1 has been shown to contribute to the modulation of various immune cell activities, resulting in the enhancement of tumor progression." (PMID 39795613, 2025). "Initially reported as an inhibitor of the oncogenic Wnt signaling pathway, DKK1 was originally considered a tumor suppressor gene." (PMID 40025612, 2025). "Previous studies have shown that DKK1 blockade can slow tumor growth in an NK cell-dependent manner, and our data also support the notion that DKK1 blockade leads to NK cell activation." (PMID 40394415, 2025). "Xenografting these cells into NOG-SCID mice showed that DKK1 expression greatly suppressed USP6-dependent tumor growth." (PMID 40348771, 2025). "To assess DKK1 expression at the tumor site, we analyzed a microarray dataset (GSE374433) composed of healthy and malignant breast tissues from ER+, HER2+, and TNBC patients." (PMID 39885132, 2025). "DKK1 inhibits β-catenin activation, thereby suppressing the Wnt signaling pathway, which is essential for tumor suppression." (PMID 39788945, 2025). "Recent studies have shown that DKK1 expression is elevated in many cancer types and contributes to tumor growth." (PMID 40025612, 2025). "Collectively, these in vivo findings show that TP-0903 reduces the growth of tumor derived from Neuro-2a cells and inhibits DKK1 expression, but insignificantly affects the body weight and histological feature of organs." (PMID 40804038, 2025). "DKK1 plays a multifaceted role in cancer progression, particularly in promoting tumor growth, metastasis, and immunosuppression." (PMID 39505867, 2024). "While bone-derived DKK1 contributes to the systemic elevation of DKK1 during tumor progression, CAFs represent the primary source of DKK1 at the tumor site, suppressing NK cell-mediated tumoricidal activity." (PMID 38659818, 2024). "The concentration of DKK1 was found to be increased by co‐culture with tumor organoids than when NFs were cultured alone." (PMID 38334454, 2024). "Positive Dkk1 staining was detected in 71% (48/68) of treated tumours, with only two cases showing strong staining." (PMID 38254908, 2024). "The candidate biomarkers HPV, p63, CD15, DKK1, and CD147 linked a tumor-promoting TME with a higher TNM classification reflecting more aggressive and metastasizing cancers." (PMID 39333233, 2024). "Taken together, the findings suggest that DKK1-SE contributes to a complex tumor microenvironment, involving increased vascular endothelium, collagen fibers, and myofibroblasts, influencing the progression of PDAC tumors in vivo." (PMID 39107271, 2024). "In the context of metastasis, DKK1 promotes the differentiation of disseminated tumor cells, which is pivotal for their outgrowth at metastatic sites." (PMID 39505867, 2024). "We showed in a previous study that Dkk1 was expressed in 70% of BC tumoural tissues from 77 women patients." (PMID 38254908, 2024). "In summary, these data suggest that patients with a tumor biology characterized by DKK1, p63 and CD15, have a reduced survival prognosis due to more aggressive growing cancers, as previously suggested." (PMID 39333233, 2024).
tumor (continued). "Comprehensive experimental validations are necessary to interpret the role of DKK1+ tumor cells in impeding the infiltration of CCL19+ fibroblasts and plasma cells into the tumor area within the context of the immune response." (PMID 39505867, 2024). "In the meanwhile, DKK1+ tumor cells accumulated in the tumor area in immune-exclusion samples, especially in the tumor boundary, inhibiting the infiltration of CCL19+ fibroblasts and plasma cells into tumor area." (PMID 39505867, 2024). "DKK1 is an inhibitor of the Wnt signaling pathway while DKK3 is generally considered to act as a tumor suppressor." (PMID 38886806, 2024). "In contrast, the presence of CD45+ immune populations in the central regions of the tumor mass was readily evident in animals following DKK1 neutralization or deletion of DKK1 in the CAFs." (PMID 38659818, 2024). "The new data demonstrate that DKK1 is highly expressed in the tumor area of immune-exclusion samples, with DCN+CCL19+ fibroblasts excluded from the tumor core." (PMID 39505867, 2024). "Lower scores for Dkk1 expression in biopsy tissues, smaller tumour size, and positive Her2 expression independently predicted a favourable R grade." (PMID 38254908, 2024). "DKK1 levels were also significantly increased 14 days post inoculation in BALB/c mice orthotopically injected with the triple-negative 4T1 tumor line." (PMID 38659818, 2024). "In the treatment of HCC, cinobufotalin has been found to reduce the mRNA and protein expression of β-catenin, as well as its target genes MMP7 and dickkopf WNT signaling pathway inhibitor 1 (DKK1), which are associated with tumor invasion and metastasis." (PMID 39354529, 2024). "DKK1’s promotion of differentiation is vital for the metastatic outgrowth of disseminated tumor cells." (PMID 39505867, 2024). "While Dkk1 was barely detectable in the tumor cell lines in vitro, Dkk1 transcripts were detected in the tumor mass 14 days post-inoculation." (PMID 38659818, 2024). "In immune exclusion samples, DKK1 was highly expressed in the tumor area, where plasma cells and CCL19+ fibroblasts were excluded and situated along the tumor boundary." (PMID 39505867, 2024). "Our study also suggests the intriguing potential of DKK1 in influencing the prognosis of patients with HNSCC by infiltrating the tumor immune system." (PMID 38376441, 2024). "In colorectal cancer, restoration of epigenetically silenced DKK1 expression inhibited tumor growth." (PMID 39107271, 2024). "The results showed that Dkk1 expression levels in treated BC tumours were lower than in untreated tumours." (PMID 38254908, 2024). "Although increasing evidences show that DKK1 promotes tumor progression in malignant tumors, DKK1 was originally annotated as a tumor suppressor." (PMID 39107271, 2024). "The further rescue study indicated that DKK1 overexpression significantly attenuated the HOTTIP-facilitated tumor cell growth and Wnt/β-catenin signaling activation." (PMID 38481876, 2024). "DKK1 modulates immune cell function in a way that contributes to an immunosuppressive tumor microenvironment and affects cell adhesion and motility to enhance metastasis." (PMID 38396744, 2024). "In summary, our findings shed light on the intra-tumor immune infiltration in HCC and underscore the role of DKK1+ tumor cells in hindering the infiltration of CCL19+ fibroblasts and plasma cells, thereby contributing to immune resistance." (PMID 39505867, 2024). "In immune exclusion samples, DKK1 exhibited notable expression within tumor areas, whereas in samples displaying immune activation, its expression levels were markedly lower." (PMID 39505867, 2024). "Elevated DKK1 levels were also linked to HPV-negative status, a high mutation load, lymph node metastasis, and late-stage tumors with high tumor grades." (PMID 38376441, 2024).